ICAM1 (intercellular adhesion molecule 1)
Diseases named in the same sentence as ICAM1 in open-access papers (continued):
Sharing a sentence is not in itself a finding about the gene and the disease.
prostate carcinoma (49 papers, 2006 to 2025). A carcinoma that arises from epithelial cells of the prostate gland. "Furthermore, targeted knockdown of E2F1 enhances the susceptibility of tumor cells to ICAM-1-mediated anti-tumor immunity against prostate cancer." (PMID 24742333, 2014). "The down-regulation of ICAM1 mediated by ectopic expression of miRNA-296-3p in prostate cancer could facilitate metastasis by reducing susceptibility of circulating tumor cells to cytotoxicity by nature killer (NK) cells though inhibition of NK cell activation and expansion." (PMID 34408980, 2021). "Furthermore, knockdown of E2F1 inhibited tumor growth of prostate cancer in vivo through increasing the susceptibility of tumor cells to ICAM-1-mediated anti-tumor immunity including enhancement of monocyte adhesion, leucocytes infiltration, as well as cytotoxicity against tumor cells." (PMID 24742333, 2014). "These authors established cell–cell communication via EV ICAM-1 as a novel mechanism by which the proto-oncogene RelB promotes prostate cancer progression." (PMID 38542421, 2024). "In contrast, it has been demonstrated that the prostate cancer PC3 cell knockdown of ICAM1 increased the sensitivity to cisplatin treatment, showing more apoptotic cells." (PMID 39201551, 2024). "The exosomal membranous form of intercellular adhesion molecule-1 (ICAM-1) (mICAM-1) of prostate cancer cells inhibits the binding of leukocytes to endothelial cells activated by tumor necrosis factor-alpha." (PMID 37242707, 2023). "E2F1 inhibited the binding of NF-κB p65 to the ICAM-1 promoter and eliminated the antitumor immune effect of ICAM-1 against prostate cancer cells." (PMID 38187112, 2023). "Consistently, a knockdown of CCN3 was found to decrease bone metastasis of prostate cancer cells since CCN3 upregulates the expression of the pro-migratory intercellular adhesion molecule 1 (ICAM-1) and promotes migration via AKT, NFKB, and other pathways." (PMID 34064589, 2021). "For example, miR-296-3p is highly expressed in human prostate cancer and can directly inhibit the expression of intercellular adhesion molecule 1 (ICAM-1)." (PMID 34084160, 2021). "This is in the basis of using ICAM-1 sequences in the formulation of TRICOM vaccines to treat prostate cancer." (PMID 30258446, 2018). "As predicted, the MREs bound to tenascin C. Another study determined that ICAM-1, an intercellular adhesion molecule, was the target of scFv MREs selected on androgen insensitive prostate cancer cells." (PMID 26436100, 2015). "E2F1 knockdown by a specific short hairpin RNA (shRNA) or small interference RNA (siRNA) increased gene transcription and protein expression of ICAM-1 in human prostate cancer cells." (PMID 24742333, 2014). "Such difference in xenografts developed from DU145/sh-E2F1 and DU145/sh-ICAM-1 cells demonstrated the opposing effects between E2F1 and ICAM-1 in tumorigenesis of prostate cancer." (PMID 24742333, 2014). "Taken together, our data provided the evidence that E2F1 influences the ICAM-1 mediated anti-tumor microenvironment immune circuit through NF-κB modulation, which regulates prostate cancer cells escape from immune responses." (PMID 24742333, 2014). "Tumor xenograft mice model with E2F1 and ICAM-1-knockdown prostate cancer cells were used to investigate the effects of E2F1 and ICAM-1 on antitumor immunity." (PMID 24742333, 2014). "This was confirmed by the observation that p85 and Akt mutants inhibited the increased migration and ICAM-1 expression in human prostate cancer cells." (PMID 23803661, 2013). "In this study, we found that AP-1 activation is involved in BK-mediated migratory ability and ICAM-1 expression in prostate cancer cells." (PMID 23803661, 2013). "Here, we reported that BK enhanced cell migration and ICAM-1 expression of human prostate cancer cells." (PMID 23803661, 2013).
prostate carcinoma (continued). "Our results indicate that BK enhances the migration of prostate cancer cells by increasing ICAM-1 expression through a signal transduction pathway that involves the B2 receptor, PI3K, Akt, and AP-1." (PMID 23803661, 2013). "A previous study has shown that AP-1 activation mediates ICAM-1 expression and metastasis in human prostate cancer cells." (PMID 23803661, 2013). "Our results suggest that BK enhanced cell migratory ability and ICAM-1 expression in human prostate cancer cells." (PMID 23803661, 2013). "Several lines of evidence in this study show that ICAM-1 is involved in BK-induced cell migration of human prostate cancer cells." (PMID 23803661, 2013). "Here, we present a new mechanism for the BK-mediated migratory ability of prostate cancer cells, i.e., by up-regulation of ICAM-1." (PMID 23803661, 2013). "Taken together, our results provide evidence that BK up-regulates migration and ICAM-1 expression of human prostate cancer cells via the B2 receptor/PI3K/Akt signaling pathway." (PMID 23803661, 2013). "In contrast, in prostate cancer, tumor cells evade NK cell attack by suppressing ICAM1 expression." (PMID 37671167, 2023). "Fundamental research on prostate cancer demonstrated that neutrophils could bind to CTCs through intercellular adhesion molecule-1 to enhance the immune-killing resistance of CTCs to NK cells, thereby promoting the immune escape of CTCs." (PMID 36465354, 2022). "PL was found to significantly inhibit the activation of NF-κB and modulate the expressions of NF-κB mediated proteins such as IL-6, IL-8, MMP-9, and intercellular adhesion molecule 1 (ICAM-1), thereby suppressing the metastatic potential of the prostate cancer cells." (PMID 36046754, 2021). "Moreover, δ-Toc prevents constitutive NF-kB activation in pancreatic cancer, and α-Toc succinate reduces NF-kB activity and ICAM-1 expression in prostate cancer cells." (PMID 33499140, 2021). "Likewise, in prostate cancer, bradykinin, which has been shown to promote tumor expansion and dissemination, enhances migration and spread by augmenting ICAM-1 expression." (PMID 30657059, 2019). "The deregulation of both ICAM1, and FTH1 was previously associated with human prostate cancer." (PMID 30925701, 2019). "For example, knockdown of ICAM-1 inhibits invasion of prostate cancer cells." (PMID 28903329, 2017). "Our results demonstrated that DT could reduce the secretion of chemokines, including CCL2, CCL5, and ICAM-1, in prostate cancer cells, and inhibit prostate cancer cell migration under the macrophages’ cultured medium." (PMID 28157698, 2017). "In the context of cancer, simvastatin mediates suppress prostate cancer PC3 micrometastasis through inhibition of integrin αvβ3 activity and suppression of the interaction between prostate cancer cell integrin αvβ3 and endothelial intercellular adhesion molecule (ICAM)-1." (PMID 26517522, 2016). "Silencing MMP9 in prostate cancer cells concomitantly inhibits ICAM-1 expression." (PMID 26513020, 2015). "This suggests that the effects of ICAM-1 upregulated by E2F1 knockdown may have important implications for the systemic treatment of prostate cancer." (PMID 24742333, 2014). "Stimulation of prostate cancer cells with BK induced mRNA and protein expression of ICAM-1." (PMID 23803661, 2013). "In this study, we further investigated whether ICAM-1 up-regulation is also involved in BK-promoted cell motility of human prostate cancer cells." (PMID 23803661, 2013). "Here, we further examined whether ICAM-1 expression is involved in BK-mediated motility of human prostate cancer cells." (PMID 23803661, 2013). "Furthermore, c-Jun siRNA abolished BK-induced cell migration and ICAM-1 expression in prostate cancer cells." (PMID 23803661, 2013). "ICAM-1 activation has been reported to mediate prostate cancers motility." (PMID 23803661, 2013). "Therefore, the BK/B2 interaction is involved in cell migration and ICAM-1 expression in human prostate cancer cells." (PMID 23803661, 2013).
prostate carcinoma (continued). "The aim of this study was to examine whether BK promotes prostate cancer cell migration via ICAM-1 expression." (PMID 23803661, 2013). "Furthermore, the fabricated brown, navy, and red PINs were employed to simultaneously detect key biomarkers of gastric, pancreatic, and prostate cancers, specifically, intercellular adhesion molecule 1 (ICAM1), carbohydrate antigen 19-9 (CA19-9), and prostate-specific antigen (PSA), respectively." (PMID 41149334, 2025). "Therefore, we investigated whether the B2 receptor mediates BK-induced prostate cancer cell migration and ICAM-1 expression." (PMID 23803661, 2013). "Furthermore, CCN3 also promoted ICAM-1 expression and cell motility of human prostate cancer cells." (PMID 23803661, 2013). "Therefore, we hypothesized that ICAM-1 may be also involved in the BK-induced migratory ability of human prostate cancer cells." (PMID 23803661, 2013). "These three types of PINs were also used in a multiplex CLFA system for the detection of ICAM1, CA19-9, and PSA, which are representative biomarkers of gastric, pancreatic, and prostate cancers, respectively." (PMID 39446245, 2024). "Many studies have revealed that high ICAM-1 expression promotes the occurrence, metastasis, and poor outcome of many kinds of carcinoma such as cervical, hepatocellular, gastric, and prostate cancer and that it might be induced by NF-κB- and AP-1-mediated pathways." (PMID 31312656, 2019). "We previously showed that HEGU and licoricidin reduce the invasion, adhesion, and migration of DU145 prostate cancer cells, as well as the secretion of MMP-9, ICAM-1, and VCAM-1." (PMID 27314329, 2016). "Targeted knockdown of E2F1 did not affect expression and phosphorylation of NF-κB and IκBα, but facilitated NF-κB binding to the ICAM-1 promoter, subsequently induced ICAM-1 transcription and production in prostate carcinoma cells." (PMID 24742333, 2014). "Targeted knockdown by interferon RNA was applied on two prostate cancer and Hela cell lines to examine the inverse correlation expression of E2F1 and ICAM-1." (PMID 24742333, 2014). "BK increased the expression of ICAM-1 through the B2 receptor, PI3K, Akt, and AP-1-signaling pathway and migration of human prostate cancer cells." (PMID 23803661, 2013). "Our data suggest that BK increases the expression of ICAM-1 and cell motility through PI3K and Akt signaling pathways in human prostate cancer cells." (PMID 23803661, 2013). "We demonstrated that treatment with a PI3K inhibitor and Akt inhibitor inhibited BK-induced cell motility and ICAM-1 expression, suggesting that PI3K/Akt activation is a requisite event in BK-increased cell migration in prostate cancer cells." (PMID 23803661, 2013). "In this assay, specific antibodies conjugated to PINs were bound to their corresponding analytes—intercellular adhesion molecule 1 (ICAM1), carbohydrate antigen 19-9 (CA19-9), and prostate-specific antigen (PSA), which are indicative of gastric, pancreatic, and prostate cancers, respectively." (PMID 39996970, 2025). "Multiple angiogenic factors are over-expressed in highly metastatic prostate cancer cell lines, including VEGF, ICAM-1, IL-8 and TGF-β2 and expression of factors such as VEGF and ICAM-1 may be dependent on MMP-9 expression." (PMID 33805598, 2021). "In prostate cancer, CCN3 induces ICAM-1 expression and thus promotes bone metastasis." (PMID 28903329, 2017). "Pretreatment of prostate cancer cells with B2 receptor, phosphatidylinositol 3-kinase (PI3K), Akt, and activator protein 1 (AP-1) inhibitors or mutants abolished BK-promoted migration and ICAM-1 expression." (PMID 23803661, 2013). "In prostate cancer, bradykinin has been shown to enhance migration and spread by augmenting ICAM-1 expression, and micrometastasis could be inhibited by blocking integrin αVβ3 and ICAM-1." (PMID 39459070, 2024). "In the current study, we did not examine whether MMP-9 also cleaved ICAM-1 in BK-mediated cell motility of prostate cancer cells." (PMID 23803661, 2013).
prostate carcinoma (continued). "In addition to the growth and progression of prostate cancer itself, research has been proposed that exosome PSGR1 might regulate MAPK and NF-κB signaling pathways involved in prostate cancer bone metastasis by targeting ICAM1, RELB, and IL1B." (PMID 41347146, 2025). "In addition, AA has been shown to induce 11 genes regulated by NFκB in a human prostate cancer cell line PC-3 including COX-2, IκBa, NFκB, granulocyte macrophage stimulating factor (GM-CSF), IL-1B, CXCL-1, TNF-α, IL-6, LTA, IL-8, PPARγ, PPARδ, and intercellular adhesion molecule 1 (ICAM-1)." (PMID 23844276, 2013).
ovarian carcinoma (48 papers, 2007 to 2025). A malignant neoplasm originating from the surface ovarian epithelium. "The significant association of HLA-DP rs3077 AA, HLA-DQ rs3920 GG, ICAM-1 rs1437 CC, and CT genotypes with increased risk of ovarian cancer (OR 43, 6, 25, and 2.6, respectively) was confirmed." (PMID 38275400, 2024). "Accordingly, nuclear Sam68 was reported to enhance the recruitment of activated NF-kB complex to the promoter of intercellular adhesion molecule-1 (ICAM-1) in the context of fatty acid deficiency in ovarian cancer." (PMID 37792222, 2024). "Sam68-dependent induction of ICAM-1 in lipophagic cells was associated with tumor progression and contributed to poor survival in patients with ovarian carcinoma." (PMID 37792222, 2024). "Recent studies have identified ICAM-1 as a potential oncogene that promotes the development of epithelial ovarian cancer (EOC); it was also found to be associated with poor survival." (PMID 31312656, 2019). "So ICAM-1 rs1437 CC and CT genotypes are good predictors for ovarian cancer; particularly CC allele." (PMID 27252704, 2016). "We found significant association of HLA-DP rs3077 AA, HLA-DQ rs3920 GG, ICAM-1 rs1437 CC, and CT genotypes with increased risk of ovarian cancer (OR = 43.5, 6, 25, and 2.6, respectively)." (PMID 27252704, 2016). "This agree with our results, where there was statistically significant association between ICAM-1 rs1437 CC and CT genotypes and ovarian cancer (OR = 25 and 2.6, respectively), so they are good predictors for ovarian cancer risk; particularly CC allele." (PMID 27252704, 2016). "For ICAM-1, the induced loss of DNA methylation in A2780 ovarian cancer cells was associated with a slight increase in gene expression." (PMID 24194590, 2014). "Moreover, HLA-DQ rs3920 and ICAM-1 rs1437 alleles varied significantly among borderline and malignant types of ovarian cancer, highlighting once more the need for an individual approach to different ovarian cancer subtypes." (PMID 38275400, 2024). "Furthermore, ICAM-1 rs1437 alleles vary significantly among the different types of ovarian cancer where T allele is expressed more among benign cases, while C allele expression increases in the aggressive types (P = 0.001)." (PMID 27252704, 2016). "Additionally, we found that HLA-DQ rs3920 and ICAM-1 rs1437 alleles vary among different groups of ovarian cancer and are good predictors for tumor type (P = 0.003 and 0.001, respectively)." (PMID 27252704, 2016). "In addition, HLA-DQ rs3920 and ICAM-1 rs1437 alleles vary significantly among different types of ovarian cancer (P = 0.003 and 0.001, respectively)." (PMID 27252704, 2016). "Indeed, HLA-class II and/or ICAM-1 SNP may influence the tumor-specific mechanisms, as the statistical analysis showed strong association between certain alleles and ovarian cancer; particularly aggressive types." (PMID 27252704, 2016). "Our findings suggest that VCAM-1 and ICAM-1 play a role in ovarian cancer recurrence, with VCAM-1 significantly elevated in tumor tissue and blood of recurrent cases." (PMID 40652770, 2025). "In particular, TAM‐derived EGF has been shown to sustain the formation of ascetic spheroids during metastasis by facilitating their interaction with ovarian cancer cells, which is mediated by αMβ2 integrin and intercellular adhesion molecule 1 (ICAM‐1)." (PMID 38411356, 2024). "Subsequently, antibody blockade of ICAM-1 in macrophages blunted spheroid formation and ovarian cancer progression in these models." (PMID 36497444, 2022). "For instance, the overexpression of endothelin B receptors (ETBR) on the tumor vasculature in ovarian cancer represses T cell trafficking by preventing ICAM-1 clustering on endothelial cells, which has a central role in T cell arrest and migration." (PMID 35211124, 2022).